UBTFL1 (upstream binding transcription factor like 1)
Description:
Essential for proliferation of the inner cell mass and trophectodermal cells in peri-implantation development.
Synonyms: C11orf27; HMGPI
Tractability: PROTAC: ubiquitination databases record sites on it.
Gene: Protein-coding gene on chromosome 11 (90,085,950 to 90,087,131, forward strand). Ensembl gene ENSG00000255009.
Subcellular location: Cytoplasm; Nucleus
Gene Ontology:
Molecular function: protein binding; RNA polymerase I core promoter sequence-specific DNA binding; RNA polymerase I general transcription initiation factor activity
Biological process: positive regulation of transcription by RNA polymerase I; transcription by RNA polymerase I; RNA polymerase I preinitiation complex assembly
Cellular component: cytoplasm; nucleus
Genetic constraint (gnomAD): Loss-of-function variants: 9 observed, 15.98 expected, observed/expected ratio (o/e) 0.56, 90% interval 0.34 to 0.98. The synonymous counts are far from expectation, so gnomAD's model fits this gene poorly and the ratio says little. Missense variants: 120 observed, 200.1 expected, observed/expected ratio (o/e) 0.6, 90% interval 0.52 to 0.7. Synonymous variants: 40 observed, 64.97 expected, observed/expected ratio (o/e) 0.62, 90% interval 0.48 to 0.8.
Homologues: Orthologues: mouse Ubtfl1 (52% identical), rat Ubtfl1 (48% identical), zebrafish ubtfl (39% identical), zebrafish ubtf (36% identical), Caenorhabditis elegans hmg-4 (12% identical), Caenorhabditis elegans hmg-3 (10% identical). Paralogues in human: UBTF (50% identical), HMGXB4 (14% identical), SSRP1 (13% identical), TOX3 (12% identical), TOX2 (11% identical), SP100 (11% identical), TOX (11% identical), SP140L (10% identical), TOX4 (10% identical), HMGB1P1 (10% identical), HMGB2 (10% identical), HMGB1 (9% identical), and 8 more.